SNHG15 (small nucleolar RNA host gene 15)
Diseases named in the same sentence as SNHG15 in open-access papers (continued):
Sharing a sentence is not in itself a finding about the gene and the disease.
tumor (continued). "Overexpression of SNHG15 can regulate AIF activity, thereby promoting tumor progression and increasing drug resistance." (PMID 37020597, 2023). "Through interaction with AIF, SNHG15, a bifunctional MYC-regulated lncRNA, induced the growth of LoVo and SW620 tumor cells in CRC." (PMID 37056344, 2023). "Small nucleolar RNA host gene 15 (SNHG15), a ceRNA of miR-141, increased the expression level of PD-L1 on GC cells, thereby improving the resistance of GC cells to tumor immune response." (PMID 36875764, 2023). "The abnormal expression of SNHG15 promoted the proliferation, invasion and epithelial–mesenchymal transition (EMT) of tumor cells as well." (PMID 32633324, 2020). "SNHG15 may, through the PI3K/AKT signaling pathway promoting tumor invasion and metastasis, and it may be a new potential prognostic marker." (PMID 38526609, 2024). "They found that SNHG15 knockdown impeded colony formation, invasion and migration of HCC cells as well as enhanced apoptosis of HCC cells, while the tumor size and volume was decreased in nude mice injected with HCC cells transfected with plasmids with low expression of SNHG15." (PMID 35629174, 2022). "In contrast, no statistical correlation was observed between SNHG15 expression and gender (P=0.30) and tumor size (P=0.77)." (PMID 32733556, 2020).
infection (6 papers, 2017 to 2026). The state of being infected such as from the introduction of a foreign agent such as serum, vaccine, antigenic substance or organism. "Knockdown of Snhg15 during TC-83 infection resulted in the suppression of ten genes, all of which were also increased during TC-83 infection along with Snhg15." (PMID 42023950, 2026). "The MAC-infection-mediated downregulation of Snhg15 seen in wild-type BMDMs was suppressed in BMDMs derived from Tlr2 knockout mice." (PMID 38711507, 2024). "Other lncRNAs (i.e., BANCR, GAS5, GSTT1-AS1, PVT1, RMRP, and SNHG15) increased at one or more time-points during infection; BANCR was highly increased in infected cells, but only at 24 h." (PMID 31547203, 2019). "Knockdown of Snhg15 during VEEV TC-83 infection resulted in the suppression of ten genes including Irf1, Junb, Atf3, Relb, Pim1, Hbegf, Ccl5, Ankrd33b, and H2-K2, all of which were also increased during TC-83 infection when the expression of Snhg15 increased in primary mouse astrocytes." (PMID 40463150, 2025).
SNHG15 also shares sentences with these, for which no sentence is quoted: glioblastoma (4 papers); liver cancer (3); colon adenocarcinoma (2); diffuse large B-cell lymphoma (2); esophageal squamous cell carcinoma (2); lymphoid neoplasm (2); nasopharyngeal carcinoma (2); rectum adenocarcinoma (2); thymoma (2); acute myeloid leukemia (1); adrenocortical carcinoma (1); blood cancers (1); cholangiocarcinoma (1); colorectal (1); diabetic cardiomyopathy (1); digestive system cancer (1); lung adenocarcinoma (1); multiple myeloma (1); oral squamous cell carcinoma (1); prostate adenocarcinoma (1); renal carcinoma (1); respiratory system cancer (1); testicular germ cell tumor (1); testicular germ cell tumours (1); thyroid tumor (1); uveal melanoma (1).